TNF (tumor necrosis factor)
Diseases named in the same sentence as TNF in open-access papers (continued):
Sharing a sentence is not in itself a finding about the gene and the disease.
Obesity (continued). "Obesity is associated with increased expression of proinflammatory cytokines such as IL-6, TNFα, and IL-1β in adipose tissue." (PMID 31828157, 2019). "Alternatively, plasma AA was positively associated with breastmilk TNF-α in women with overweight or obesity." (PMID 31141526, 2019). "Binding to RAGE can also increase reactive oxygen species (ROS), activate inflammatory signaling (tumor necrosis factor alpha, TNF-α), and induce insulin resistance, which is often associated with obesity." (PMID 31847322, 2019). "A previous study suggested that obesity-related adipocyte inflammatory condition can suppress β-Klotho expression by tumor necrosis factor-alpha and impair FGF21 function in adipose tissue causing glucose intolerance." (PMID 31582974, 2019). "In childhood-onset SLE increased serum tumor necrosis factor (TNF) levels are associated with obesity and body fat content." (PMID 31552019, 2019). "The adipokines such as leptin, adiponectin, IL-6, and TNF-α show prominent effects on adipocyte metabolism and utilization of insulin and, therefore, exhibit a strong association with obesity and related metabolic disease." (PMID 31597283, 2019). "A central role for TNF-α in obesity-associated early pancreatic tumor promotion has been demonstrated by genetic deletion of tumor necrosis factor receptor 1A (TNFR1)." (PMID 31277269, 2019). "Multiple studies revealed that excessive TNF-α concentrations have been implicated in the development of insulin resistance in obesity and type 2 diabetes." (PMID 29955954, 2019). "Insulin resistance was further associated with high inflammatory markers (hsCRP and TNF-α), visceral fat and obesity." (PMID 35538928, 2019). "Both human and mouse model studies have reported the increased TNF-α levels in obesity and association with BMI." (PMID 31718015, 2019). "Both PAH and obesity are regarded as inflammatory conditions associated with induction of cytokines (e.g. IL-6 and TNF-α) and pro-inflammatory enzymes (e.g. iNOS)." (PMID 30689673, 2019). "TNFα production is elevated in obesity-induced inflammatory states and is implicated as a major mediator of muscle atrophy." (PMID 31312114, 2019). "Levels of E-selectin are also increased in obesity, specifically in association with increased visceral adiposity and increased markers of TNF-α activation." (PMID 31550292, 2019). "Obesity and psoriasis share common pathogenic mechanisms, including increased proinflammatory cytokines (IL-1, IL-6, TNF-α, and adiponectin)." (PMID 31275060, 2019). "At PEEP = 2 cmH2O, alveolar collapse was increased and TNF-α levels in lung tissue were higher in obese animals, probably due to the enhanced lung inflammatory response associated with obesity." (PMID 31920717, 2019). "Obesity-associated hyperplasia and hypertrophy of adipose tissue cause an increase in proinflammatory cytokines, such as tumor necrosis factor alpha (TNF-α) and interleukin-6 (IL-6)." (PMID 31450844, 2019). "We believe that in addition to its role in the associations of obesity with hyperandrogenism, chronic inflammation, and other phenotypes, TNF-α is also an important regulator of adipocyte differentiation and lipid recruitment." (PMID 31170164, 2019). "The adipose tissue microenvironment in obesity enters into a proinflammatory state, which can cause adipocyte dysfunction through the actions of cytokines, such as tumor necrosis factor α (TNFα)." (PMID 30741926, 2019). "A number of signals, including those associated with obesity, such as cytokines like TNF-α and Toll-like receptor (TLR) agonists of pathogenic or dietary origin (e.g., in the presence of excess free fatty acids), can boost NF-κB pathways." (PMID 31627295, 2019). "Adipocyte hypertrophy is a classical manifestation of obesity and is directly associated with the aetiology of macrophage infiltration, hypoxia, secretion of pro-inflammatory cytokines (e.g., TNF-α, IL-6, IL-1β) and reduced production of adiponectin." (PMID 31133986, 2019).
Obesity (continued). "Excessive formation of tumor necrosis factor-α (TNF-α), a pro-inflammatory cytokine, has been implicated in the development of insulin resistance in obesity and type-2 diabetes." (PMID 29955954, 2019). "Inflammatory responses mediated by TNF-α signaling in the hypothalamus are integrally involved in obesity in genetical leptin–deficient obese models." (PMID 31739649, 2019). "TNFα, a potent NF-κB activator, is closely linked to loss of muscle mass in various inflammatory conditions such as obesity." (PMID 31312114, 2019). "Previous studies have shown that as obesity increases, skeletal muscle loss leads to an increase in inflammatory adipocytes, such as leptin, tumor necrosis factor alpha (TNF-α), and interleukin (IL-6), and reduces concentrations of adiponectin or IL-15." (PMID 31269909, 2019). "TNF-α is an inflammatory cytokine that has been linked with obesity, T2DM, hypertriglyceridemia, decreased HDL-cholesterol and CVD, among other inflammatory and infectious diseases." (PMID 31546768, 2019). "We next measured the mRNA expressions of tumor necrosis factor-α (Tnfa) and Il6, encoding cytokines that are considered to be important mediators of insulin resistance in obesity." (PMID 31577826, 2019). "These events are considered contributing factors for obesity-associated inflammation in which pro-inflammatory cytokines like TNF-α and IL-6 are increasingly expressed and anti-inflammatory markers such as adiponectin are downregulated." (PMID 31551782, 2019). "Here, we analyzed TNFα signaling pathway and its role in Ca2+ signaling dysfunction in male and female rodent models of type 2 diabetes linked to obesity (db/db mice) using confocal microscopy in freshly isolated cardiomyocytes." (PMID 30792662, 2019). "TNF-α is a key secretory cytokine in adipocyte tissue, whose role in obesity has been linked to proinflammation and insulin resistance." (PMID 31828124, 2019). "We sought to evaluate the association between obesity and response to anti-tumor necrosis factor-α (TNF) agents, through a systematic review and meta-analysis." (PMID 29771924, 2018). "TNF-α has been linked to obesity-related insulin resistance, as it inhibits intracellular signaling from the insulin receptor and is considered a major factor in the development of metabolic diseases." (PMID 30597839, 2018). "Regular training, in contrast, reduces systemic low-grade inflammation and hepatic inflammation associated with NAFLD and obesity and alters the immune state of the liver, making it less susceptible to acute TNF-mediated injury." (PMID 29710765, 2018). "Tumor necrosis factor α (TNF-α) is a well-known marker associated with induction of obesity related to insulin resistance and dyslipidemia." (PMID 30445784, 2018). "We used TNF−/− mice to examine the role of TNF in mediating obesity‐associated changes to inflammatory Ly6Chigh monocytes." (PMID 30548217, 2018). "This is of great interest, as TNF-α has been frequently linked to the comorbidities related to obesity." (PMID 29409496, 2018). "It is widely accepted that obesity can cause systemic low-level inflammation and increase the concentration of inflammatory factors such as TNF-α and LPS in plasma." (PMID 30483238, 2018). "This association was first understood when murine obesity was linked with increased production of the inflammatory, insulin desensitising cytokine: tumour necrosis factor-α (TNF-α)." (PMID 29479350, 2018). "Pulmonary fibroblasts were challenged with ω-3 polyunsaturated fatty acids (PUFAs), ω-6 PUFAs, saturated fatty acids (SFAs) or the obesity-associated cytokine TNFα." (PMID 30390648, 2018). "Previous researches have shown that TNF-α gene locus contributes to the pathogenesis of obesity and obesity-associated hypertension both in males and females." (PMID 29636702, 2018). "In contrast, studies on Caucasian and Chinese populations found correlations between TNF-α 308 G allele and obesity risk." (PMID 30338250, 2018).
Obesity (continued). "Some inflammatory cytokines such as interleukin-6 (IL-6) and Tumor necrosis factor-α (TNF-α) have also been implicated in obesity-related CKD." (PMID 30359237, 2018). "TNFα production is associated with dyslipidemia in many metabolic disorders (atherosclerosis, insulin resistance, obesity, and diabetes) and in cardiovascular disease." (PMID 30161232, 2018). "In turn, M1 cells express Itgax and high levels of iNOS, TNF-α, and IL-6, which impede insulin signaling in adipocytes and promote obesity-associated inflammation and insulin resistance." (PMID 29415997, 2018). "Human obesity is often associated with profound changes in the production of adipose tissue-derived factors, such as leptin, adiponectin, and tumor-necrosis factor alpha (TNF-α)." (PMID 29954158, 2018). "In mouse models, it has been shown that HFDs and obesity can activate hepatic NF-κB which causes hepatic inflammation and increases the levels of IL-6, IL-1β, and TNF-α." (PMID 30026676, 2018). "Levels of interleukin-1β, interleukin-6, interleukin-8, interferon-γ, and tumor necrosis factor-α were associated differently with patient-related characteristics (such as age, sex, obesity, and medical comorbidities)." (PMID 29581859, 2018). "Individuals with obesity or GDM have higher levels of pro-inflammatory cytokine tumor necrosis factor α (TNF-α) in the circulation, which is linked to impaired β-cell function as well as β-cell de-differentiation." (PMID 30400566, 2018). "In turn, the proinflammatory cytokines including IL-6 and TNF-α can be promoted by resistin, thus decreasing obesity-associated inflammation." (PMID 30050954, 2018). "On meta-analysis, across included IMIDs and across all anti-TNF agents, obesity was associated with 60% higher odds of failure of index anti-TNF therapy (OR, 1.60; 95% CI, 1.39–1.83), with substantial heterogeneity (I2 = 71%)." (PMID 29771924, 2018). "A possible mechanism refers to obesity-associated inflammation and suggests that increased expression of proinflammatory cytokines, for example, interleukin-6 and tumor necrosis factor-α, is associated with cognitive decline." (PMID 30159333, 2018). "TNF-α is a key pro-inflammatory cytokine associated with the pathology of obesity-linked vascular and metabolic disorders." (PMID 29636702, 2018). "While multiple factors contribute to obesity-associated cancers, we will only focus on the role of obesity-induced TNFα and IL-6 signaling in the promotion and development of hepatocellular carcinoma (HCC) and colorectal cancer (CRC) within this review." (PMID 30591653, 2018). "Previously, chronic, unresolved inflammation in obesity has been linked to local and systemic production of pro-inflammatory cytokines, particularly C-reactive protein, IL-6, TNF-α, as well as chemotactic and adipokine signaling molecules." (PMID 29738558, 2018). "Obesity is associated with latent inflammatory responses indicated by an elevated expression of pro-inflammatory cytokines such as Il1, Il6, and TNFα." (PMID 30333974, 2018). "Some authors demonstrated that obesity is associated with an inflammatory process, characterized by increased circulating levels of inflammatory cytokines such as TNF-α, IL-6, and C-reactive protein (CRP)." (PMID 29780825, 2018). "They demonstrated that resistin, leptin, and TNF-α are associated, independently of obesity and waist circumstance, with chronic venous disease." (PMID 29720688, 2018). "For instance, LXA4 inhibits IL-6, TNF-α, and ROS production thus hampers obesity-associated inflammation and has an anti-diabetic effect." (PMID 30360467, 2018). "The contribution of TNFα and IL-6 signaling to obesity-associated insulin resistance is well studied in conditional mouse models, but still reveals contradictory outcomes." (PMID 30591653, 2018). "Taken together, TNFα and IL-6 signaling in obesity-associated inflammation point towards complex, temporal, and cell-type-specific functions in the development of insulin resistance." (PMID 30591653, 2018).
Obesity (continued). "In a case-control study of a Korean population, G allele carriers of single-nucleotide polymorphism (SNP) rs361525 in the TNF-α gene showed an association with overweight/obesity susceptibility." (PMID 30134857, 2018). "Apart from insulin resistance, obesity-associated hypertension led to an increase in TNF-α in a French Canadian cohort." (PMID 30114249, 2018). "Previous studies have shown that PTP1B expression is increased by TNFα, the levels of which are often associated with increased inflammation seen with obesity." (PMID 30043179, 2018). "TNF-α is one of the earliest pro-inflammatory cytokines identified and its abnormally elevated levels are associated with obesity, insulin resistance and T2D." (PMID 30577684, 2018). "The association between obesity and chronic inflammation is suggested by several observations, such as the production of TNF-α and IL-6 by adipocytes in obese mice and humans as well as the presence of immune cells (i.e., macrophages) in adipose tissue." (PMID 30201891, 2018). "For instance, adipokines, such as leptin, TNF-alpha and resistin, have a pro-inflammatory role and are associated with an increased risk of obesity comorbidities such as T2D and cardiovascular diseases." (PMID 30451909, 2018). "Of note, elevated adipose tumor necrosis factor (TNF) is a feature of the obesity-associated pro-inflammatory milieu that is known to repress the expression of Slc2a418, Plin119 and Klb20; all of which were enhanced in exercise-trained Atg7h&mKO mice." (PMID 28801668, 2017). "It has been shown that obesity is associated with pro-inflammatory cytokines, including tumor necrosis factor-α (TNF-α), which is known to affect FLG levels in the skin, and with increased TEWL." (PMID 28592289, 2017). "Obesity is associated with elevated levels of TNF-α in plasma and adipose tissue, but excess weight loss leads to normalization of this parameter." (PMID 28103807, 2017). "Obesity causes lipid accumulation in adipocytes that can increase the production of proinflammatory cytokines such as TNF-α, IL-6, and IL-1β, and this obesity-associated chronic low-grade inflammation leads to insulin resistance." (PMID 29082259, 2017). "The ISR has been recently shown to be the main cause of liver failure due to uncontrolled hepatocytes apoptosis triggered by TNF-α, as demonstrated for several liver diseases, such as acute liver injury, obesity-associated fatty liver, and viral hepatitis." (PMID 28659918, 2017). "Inflammatory mechanisms are linked with obesity and associated with the production of proinflammatory cytokines such as IL-6 and TNFα." (PMID 29269995, 2017). "Lesion incidence was associated with factors related to obesity, namely percentage body fat, plasma leptin concentration and markers associated with chronic inflammation (TNFα)." (PMID 29166409, 2017). "Inflammation of adipose tissue in obesity is associated with increased IL-1β, IL-6 and TNF-α secretion and proposed to contribute to insulin resistance." (PMID 27840174, 2017). "Obesity also induces “smoldering” inflammation causing a permanently elevated level of cytokines (TNF alpha, IL-6, CRP) which promote tumurigenesis." (PMID 26951106, 2016). "Obesity is associated with a state of chronic inflammation characterized by an abnormal production of proinflammatory mediators by the fat tissue, such as TNF-α, as shown in our work." (PMID 26985993, 2016). "Blood pressure and obesity measurements were also negatively associated after 6 months of TNF-α blockade." (PMID 27293954, 2016). "The main results of these studies are that TNF −308G>A was associated with an increased risk of obesity and dyslipidaemia, and carriers of the mutated allele appeared to be more responsive to dietary fat intake." (PMID 26999109, 2016). "Obesity was associated with higher sICAM-1 (p≤0.015), tumor necrosis factor-α (TNFα), interleukin-6 (IL-6), and high-sensitivity C-reactive protein (hs-CRP), p<0.001." (PMID 27459718, 2016).
Obesity (continued). "In fact, obesity is associated with a hyperexpression of TNF-α and other adipokines (e.g., IL-6, leptin, adiponectin) and transforming growth factor-β, which leads to a chronic proinflammatory state." (PMID 27964760, 2016). "Obesity causes an abnormal expression of adipokines (e.g., tumor necrosis factor-α [TNF-α], interleukin-6 [IL-6], adiponectin, leptin), which leads to a proinflammatory status." (PMID 27964760, 2016). "We also determined several notable adipokines implicated in obesity and obesity-related metabolic disorders, which included leptin, IL-6, TNF-α, and adiponectin." (PMID 27616737, 2016). "Obesity causes a low-grade inflammation and is associated with a chronic inflammatory response and increased levels of tumor necrosis factor-α (TNF-α), interleukin-6 (IL-6) and/or C-reactive protein (CRP)." (PMID 27136447, 2016). "Increased production of TNF-α has also been widely associated with obesity-related insulin resistance and abnormal vascular reactivity, the vasculature being an important target of TNF-α and closely linked to diabetic micro- and macro-complications." (PMID 28933404, 2016). "Inflammatory cytokine release from adipose tissue and elevated inflammatory cytokine levels including TNF-α and IL-6 have been associated with obesity." (PMID 27919232, 2016). "The finding of higher levels of plasma CRP, TNF-a and IL-6 in the obese is also consistent with the findings of others suggesting the presence of chronic, systemic inflammation associated with obesity." (PMID 27513854, 2016). "While there are numerous mechanisms implicated in the development of NASH, as in obesity, low adiponectin and increased TNF-α levels are hallmarks of the condition." (PMID 27128935, 2016). "Obesity is also associated with peripheral neuropathy mediated muscle atrophy or direct induction of muscle atrophy through TNF-α mediated pathways, thereby increasing muscle weakness." (PMID 27746742, 2016). "It has been confirmed that concentrations of pro-inflammatory cytokines such as TNF-α, IL-6 and CRP are elevated in obese subjects and elevated TNF-α, IL-6 are associated with obesity related insulin resistance." (PMID 27409634, 2016). "The adipokines resistin and TNF-α regulate the lipid and glucose metabolisms and their elevated levels have been associated with the progression of obesity and diabetes." (PMID 27775654, 2016). "IL-15 induces the expression pro-inflammatory cytokines such as IL-6 and TNFα from macrophages that are implicated in the pathogenesis of obesity-associated metabolic syndrome." (PMID 27684068, 2016). "Obesity (BMI >30 kg/m2 or body fat ≥32% in females or ≥25% in males) was associated with higher sICAM-1 (p≤0.015), TNFα, IL-6, and hsCRP (p<0.001)." (PMID 27459718, 2016). "Obesity was associated with higher levels of TNFα (p = 0.008), IL-6 (p<0.001), hsCRP (p<0.001), and adiponectin (p = 0.005)." (PMID 27459718, 2016). "The first indication that inflammatory mediators are associated with obesity was the discovery of the increased expression of the pro-inflammatory cytokine tumor necrosis factor (TNF) α in adipose tissue of obese mice almost two decades ago." (PMID 26263971, 2015). "The predicted network comprised several TFs with well-characterized roles in obesity-induced inflammation and three miRNAs that were directly or indirectly linked to TNF-α." (PMID 25887648, 2015). "Given that obesity is associated with chronic low-grade inflammation, we examined the expression of pro- and anti- inflammatory cytokines TNF-α and IL-10 respectively." (PMID 26588700, 2015). "TNF-α is pro-inflammatory and causes a risk lipid profile by increasing the level of triglycerides and LDL, suggesting that TNF-α is associated with obesity." (PMID 25954207, 2015). "Inflammatory mediators such as TNFα and IL-6 are highly associated with the development of insulin resistance in the setting of obesity." (PMID 26090470, 2015).